SIRT3 (sirtuin 3)
Diseases named in the same sentence as SIRT3 in open-access papers (continued):
Sharing a sentence is not in itself a finding about the gene and the disease.
melanoma (continued). "Previously, we have demonstrated that SIRT3 was constitutively upregulated in human melanoma and its inhibition resulted in anti-proliferative effects in vitro in human melanoma cells and in vivo in human melanoma xenografts." (PMID 33937086, 2021). "We have earlier demonstrated that SIRT3 overexpression promotes the proliferative potential of Hs294T melanoma cells, in vitro." (PMID 33937086, 2021). "We found that SIRT3 overexpressing melanoma cells demonstrated significant increase in tumorigenicity, measured by both tumor volume and weight." (PMID 33937086, 2021). "We have previously demonstrated that SIRT3 knockdown in NRAS-mutant SK-MEL-2 human melanoma cells inhibited tumor growth in a subcutaneous implanted Nu/Nu nude mouse model." (PMID 33937086, 2021). "shRNA-mediated knockdown of SIRT3 in SK-MEL-2 melanoma cells resulted in alteration in a number of metabolism-related genes." (PMID 33937086, 2021). "Overall these results suggest that modulation in these genes in response to SIRT3 inhibition results in metabolic shift in melanoma cells providing lesser fuel for proliferating cells." (PMID 33937086, 2021). "We have recently demonstrated that SIRT3 was overexpressed in human melanoma, and its small hairpin RNA (shRNA) mediated knockdown provoked the senescence and growth inhibition in melanoma cells, in vitro and in vivo." (PMID 33937086, 2021). "Overall, our study identified the involvement of SIRT3 in altering the metabolic phenotypes in melanoma." (PMID 33937086, 2021). "Here, we expanded our work to confirm our previous results of SIRT3 knockdown in BRAF-mutant human melanoma cell line G361." (PMID 33937086, 2021). "We found that short-hairpin RNA (shRNA) mediated SIRT3 knockdown in G361 melanoma cells showed diminished tumorigenesis in immunodeficient Nu/Nu mice." (PMID 33937086, 2021). "The pro-proliferative role of SIRT3 was also shown in the xenograft experiment with SIRT3 overexpressing melanoma cells in Nu/Nu nude mice." (PMID 33937086, 2021). "Based on available data from our laboratory and elsewhere, both SIRT1 and SIRT3 appear to play important roles in melanoma progression." (PMID 33178616, 2020). "Sirt3 was shown to be overexpressed in human melanoma cell lines and in clinical melanoma tissue samples." (PMID 33091721, 2020). "Further, SIRT3 knocked down in SK-MEL-2 melanoma cells, when implanted in nude mice, resulted in a significant decrease in tumorigenicity." (PMID 33178616, 2020). "In a recent study, we have shown that dual inhibitor of SIRT1 and SIRT3 by 4′-bromo-resveratrol had significant anti-proliferative effects against melanoma cells." (PMID 33178616, 2020). "In this article, we have presented a case for the combined inhibition of SIRT1 and SIRT3 for melanoma management." (PMID 33178616, 2020). "Sirt3-MnSOD axis is therefore important for cell proliferation and survival and thus can provide new therapeutic target to fight melanoma." (PMID 33091721, 2020). "Overall, these studies suggest that both SIRT1 and SIRT3 regulate cellular metabolic homeostasis, further emphasizing the importance of targeting these two sirtuins in melanoma." (PMID 33178616, 2020). "Depletion of Sirt3 resulted in senescence induction, while its overexpression lead to the proliferation of melanoma cells." (PMID 33091721, 2020). "Further, lentiviral mediated short hairpin RNA (shRNA) knockdown of SIRT3 in melanoma cells was found to decrease cell proliferation, colony formation, and cell migration." (PMID 33178616, 2020). "A study from our laboratory demonstrated that SIRT3 is overexpressed in human melanoma tissues and cell lines." (PMID 33178616, 2020).
melanoma (continued). "Recent studies from our laboratory together with other publications suggest the pro-proliferative roles of SIRT1 and SIRT3 in melanoma." (PMID 33178616, 2020). "In accordance with its anti-cancer effects, Sirt3 was enhanced in arg-ii−/− melanoma cells." (PMID 40177131, 2025). "In melanoma cells with suppressed SIRT3, OGDH expression was found reduced." (PMID 37844995, 2023). "Considering the metabolic plasticity observed in melanoma, further examination of the role SIRT3 plays in maintaining the equilibrium of these bioenergetic pathways could lead to a better understanding of how SIRT3 suppression or induction could affect tumors." (PMID 34831420, 2021). "Utilizing RT-qPCR and Wes ProteinSimple analyses, we found modulation in the markers of cell proliferation (PCNA), survival (Survivin) and angiogenesis (VEGF) in response to SIRT3 manipulation, further supporting the pro-proliferative role of SIRT3 in melanoma." (PMID 33937086, 2021). "Compared with melanocytic nevi, melanoma tissues show a significant overexpression of SIRT3." (PMID 34831420, 2021). "Conversely, SIRT3 overexpressing Hs294T melanoma cells showed increased tumor growth." (PMID 33937086, 2021). "Collectively, these results suggest that inhibition of SIRT3 modulates cellular metabolism that may ultimately lead to an anti-proliferative response in melanoma cells." (PMID 33937086, 2021). "It is important to mention here that melanoma cells generate high ROS as a consequence of distorted melanosome structure, and thus, predicted inhibition of ROS supports the antitumor effect in response to SIRT3 inhibition in melanoma." (PMID 33937086, 2021). "Also, forced overexpression of SIRT3 in BRAF-mutant Hs294T-xenografted mouse model promoted tumorigenesis in melanoma." (PMID 33937086, 2021). "We found that SIRT3 inhibition significantly modulates genes related to glycolysis, gluconeogenesis, Krebs cycle and Pentose phosphate pathway, suggesting that inhibition of SIRT3 hampers cellular metabolism, which eventually hinders the proliferative potential of melanoma cells." (PMID 33937086, 2021). "Therefore, we used archival tumor samples from our previous study, which utilized SIRT3 knockdown in SK-MEL-2 melanoma cells xenografted in Nu/Nu mice." (PMID 33937086, 2021). "Therefore the use of SIRT3 as a potential target for melanoma management needs to be carefully investigated." (PMID 33937086, 2021). "Furthermore, short hairpin RNA knockdown of SIRT3 in melanoma led to favorable effects including reduced cell proliferation and migration, indicating possible therapeutic options." (PMID 34831420, 2021). "Thus, to analyze the effects of SIRT3 knockdown on metabolic regulators in melanoma cells, we utilized glucose metabolism PCR array." (PMID 33937086, 2021). "While the suppression of SIRT3 counters the growth of melanoma cells, the induction of SIRT3 also could be favorable in certain treatment-resistant melanomas." (PMID 34831420, 2021). "Overall, these data are consistent with the pro-proliferative role of SIRT3 in melanoma." (PMID 33937086, 2021). "Examining SIRT3 activators in BRAF inhibitor-resistant melanoma provided a model for how cancers with defective mitochondria, traditionally resistant to current therapies, may be targeted." (PMID 34831420, 2021). "The demonstrated roles of SIRT1 and SIRT3 in melanoma suggest that their inhibition may be useful in melanoma management." (PMID 33178616, 2020). "In addition, the experimental overexpression of SIRT3 via plasmids in Hs294T human melanoma cells and immortalized melanocytes led to both enhanced proliferation and colony formation in the melanoma cells and increased proliferation in melanocytes, evidence of the role of SIRT3 in melanoma growth." (PMID 34831420, 2021). "Similarly, the mitochondrial sirtuin SIRT3 also appears to be involved in melanoma progression." (PMID 33178616, 2020). "In addition, SIRT3 has a pro-proliferative function in human melanoma cells." (PMID 31199782, 2019).
melanoma (continued). "Earlier, we have demonstrated that chemical inhibition of SIRT3 along with SIRT1 decreased aerobic glycolysis (glucose uptake, lactate production and NAD+/NADH ratio) in melanoma cells." (PMID 33937086, 2021). "As melanoma cells can preferentially use a combination of glycolysis and oxidative phosphorylation, examining when to suppress (countering respiration-dependent growth) or induce (targeting weaknesses in ROS detoxification in treatment-resistant melanomas) SIRT3 could be helpful." (PMID 34831420, 2021). "Sirt3, a major mitochondrial NAD+-dependent deacetylase, which upregulates the antioxidant enzyme MnSOD, is important for melanoma survival." (PMID 33091721, 2020). "However, further studies are required to validate SIRT3 as a therapy target in suitable genetically engineered and/or patient-derived xenografts (PDX) models of melanoma." (PMID 33937086, 2021). "Similar to SIRT1 and SIRT3, SIRT6 has been shown to possess a pro-proliferative role in melanoma." (PMID 33178616, 2020). "This interaction between SIRT3 and glutamine metabolism would be interesting to study in other cancers, such as melanoma, where inhibiting glutamine transport has been considered as a method of suppressing melanoma growth in both wild-type BRAF and BRAF-inhibitor-resistant melanoma." (PMID 34831420, 2021). "However, whether Arg-II, Sirt3 and mtROS form a network affecting melanoma as well as other tumour cell growth and malignancy has not been studied." (PMID 40177131, 2025). "Though exogenous forced overexpression of SIRT3 may not represent physiologic phenomena as it generates supraphysiological SIRT3 levels, our results support the pro-proliferative function of SIRT3 in melanoma, further validating our earlier study." (PMID 33937086, 2021).
cervical cancer (14 papers, 2018 to 2025). A primary or metastatic malignant neoplasm involving the cervix. "PIK3CA mutations induce the β-catenin/SIRT3 signaling pathway thereby promoting glycolysis and proliferation of cervical cancer cells, thereby accelerating cancer progression." (PMID 38706901, 2024). "The evidence suggests that these two hotspot mutations induce glycolysis in cervical cancer cells via the β-catenin/SIRT3 signaling pathway." (PMID 34193921, 2021). "A luciferase assay was used to determine whether SIRT3 promotor was regulated by β-catenin in cervical cancer cells with PIK3CA E542K and E545K mutations." (PMID 30547809, 2018). "In fact, a recent report indicated that PIK3CA mutations promote glycolysis and proliferation by inducing the β-catenin/SIRT3 axis in cervical cancer." (PMID 36091047, 2022). "Studies have shown that highly expressed PD-L1 in cervical carcinoma cells can promote the growth and metastasis of cervical cancer through the ITGB4/SNAI1/SIRT3 pathway." (PMID 36478746, 2022). "In cervical cancer, SIRT3 significantly promotes the FA synthesis reprogramming by up-regulating acetyl-CoA carboxylase (ACC1)." (PMID 35832551, 2022). "We found that Fra-1 overexpression restored mitochondrial function in cervical cancer cells via the SIRT3 signaling pathway, and Fra-1 increased the expression of IDH2 and SOD2." (PMID 33102485, 2020). "It was reported that PD-1 could promote lymph node metastasis in cervical cancer via activating integrin β4/SNAI1/SIRT3 axis." (PMID 34666670, 2021). "Furthermore, the expression of SIRT3 was adversely related to β-catenin in cervical cancer tissues and xenograft models by IHC." (PMID 30547809, 2018). "Consequently, we inferred that SIRT3 might be involved in glucose metabolism in cervical cancer cells with mutant PIK3CA, which was adversely regulated by β-catenin." (PMID 30547809, 2018). "The results indicated that Fra-1 up-regulated the expression of SIRT3, which led to changes in IDH2 and SOD2 expression as downstream molecules, and finally reduced the ROS content in cervical cancer cells." (PMID 33102485, 2020). "Therefore, we examined the effect of Fra-1 overexpression on SIRT3, IDH2, and SOD2 expression in cervical cancer cells." (PMID 33102485, 2020). "Consistently, although SIRT3 could enhance invasion and metastasis by improving the expression of FASN in cervical cancer, TCGA-based results did not reveal a correlation between high expression of FASN and poor outcome for UCEC." (PMID 34879004, 2021).
glioblastoma (14 papers, 2019 to 2025). The most malignant astrocytic tumor (WHO grade IV). "We previously demonstrated that targeted knockdown of SIRT3 sensitized glioblastoma to ferroptosis by promoting mitophagy and inhibiting SLC7A11." (PMID 40298644, 2025). "Preclinical studies have found that Ex-4 significantly upregulates Sirt3 expression in glioblastoma by activating the GLP-1R, which subsequently inhibits the growth, migration, invasion, and epithelial-mesenchymal transition of glioma cells." (PMID 40140925, 2025). "This leads to potential novel targets for future investigations and emphasizes the critical function of SIRT3 in mitochondrial metabolism and its broader implications for cellular energetics in glioblastoma." (PMID 40710366, 2025). "Lysine acetylation significantly influences the metabolic phenotype of glioblastoma cells, and SIRT3 is essential for regulating the balance of metabolic processes in these cancer cells." (PMID 40710366, 2025). "In glioblastoma cells, SIRT3 expression is significantly induced after radiation exposure, indicating an adaptive response to therapy." (PMID 40710366, 2025). "SIRT3 is identified as a crucial enzyme in glioblastoma cells, regulating mitochondrial metabolism by modulating the acetylation of lysine residues on mitochondrial enzymes." (PMID 40710366, 2025). "SIRT3 primarily functions in mitochondrial metabolism regulation and is significantly upregulated in glioblastoma tissues." (PMID 40710366, 2025). "We also found that SIRT3 functioned in the process of autophagic degradation in glioblastoma stem cells." (PMID 40298644, 2025). "Our findings underscore the pivotal role of SIRT3, a mitochondrial deacetylase, in modulating metabolic enzymes, thus influencing the metabolic orientation of glioblastoma cells." (PMID 38542426, 2024). "Our investigation into the effects of SIRT3 inhibition on glycolytic U87MG and oxidative T98G glioblastoma cell lines unveils critical differences in their acetylation patterns, shedding light on the nuanced roles of SIRT3 in metabolic regulation." (PMID 38542426, 2024). "To delve into the impact of SIRT3 inhibition on protein expression across glioblastoma cell lines with distinct metabolic profiles, we selectively inhibit SIRT3, employing 3-TYP." (PMID 38542426, 2024). "As a member of the mammalian sirtuins family, Sirt3 is a mitochondrion-localized histone deacetylase, which is highly expressed in mitochondria-rich tissues and plays a key regulatory role in the development of glioblastoma." (PMID 40140925, 2025). "Targeting glutamine metabolism to induce the autophagic degradation of SIRT3 could be a novel strategy to eliminate GSCs and overcome glioblastoma resistance to therapy." (PMID 40710366, 2025). "Thus, it was demonstrated by Park and colleagues that interplay between TRAP1 mitochondrial chaperone and SIRT3 (mitochondria deacetylase sirtuin-3) increased adaptation to stress and maintained the stemness of the glioblastoma cells." (PMID 39015084, 2024). "In subsequent sections, we delve deeper into the differential impacts of SIRT3 inhibition on the proteomic and acetylation profiles of these metabolically distinct glioblastoma cell lines, unveiling insights into the mitochondrial and cellular response mechanisms." (PMID 38542426, 2024). "In addition, it has been reported that atlodes atlodes, a traditional Chinese medicine, can inhibit the occurrence and development of glioblastoma multiforme (GBM) by up-regulating SIRT-3, but further clinical verification is still needed." (PMID 35906622, 2022). "However, it was also proposed that TRAP1 is activated by SIRT3-dependent deacetylation in a glioblastoma model, making it difficult to draw a comprehensive picture." (PMID 35393510, 2022). "Overall, SIRT3 protects GBM cells from ferroptosis through mechanisms involving mitophagy and the regulation of SLC7A11, making it a promising therapeutic target in combination with ferroptosis induction for treating glioblastoma." (PMID 40710366, 2025).
glioblastoma (continued). "In glioblastoma (GBM), SIRT3 inhibition triggers mitophagy and simultaneously downregulates the expression of the ferroptosis antagonist SLC7A11, sensitizing tumor cells to ferroptosis." (PMID 40943150, 2025). "Sirtuin 3 (SIRT3) is the main mitochondrial deacetylase, and we previously demonstrated that targeting SIRT3 sensitized glioblastoma to ferroptosis by promoting mitophagy and inhibiting SLC7A11." (PMID 40298644, 2025). "Glioblastoma cells expressing a mutant SIRT3 lacking phosphorylation sites show reduced mitochondrial function and increased radiation sensitivity." (PMID 40710366, 2025). "Our findings suggest that glioblastoma cells upregulate affected mechanisms to mitigate this impact in response to SIRT3 inhibition, regardless of their primary metabolic pathway." (PMID 38542426, 2024). "Moreover, it has been proposed that SIRT3 activates the mitochondrial chaperone TRAP1, thus contributing to the maintenance of cancer stem cells in a glioblastoma model." (PMID 35393510, 2022).
injury (14 papers, 2017 to 2025). Damage inflicted on the body as the direct or indirect result of an external force, with or without disruption of structural continuity. "Given that SIRT3 is mainly localized in the mitochondrial matrix, SIRT3 may affect the course of I/R-induced kidney injury, which is associated with mitochondrial dysfunction." (PMID 32932720, 2020). "In neuron-specific Sirt3 knockout mice, FNDC5 fails to rescue TBI-induced mitochondrial damage and brain injuries, suggesting FNDC5/irisin plays a protective role against acute brain injury by promoting SIRT3-dependent mitochondrial biogenesis." (PMID 41373506, 2025). "In particular, the deSUMOylation of sirtuin-3 (Sirt3) restores mitochondrial function, reduces oxidative stress, and prevents apoptosis induced by hepatic ischemia/reperfusion injury." (PMID 39588331, 2024). "In addition, a cascade of SIRT3 pathways plays an essential role in microglial activation following brain injury." (PMID 37009480, 2023). "The mitochondrial respiration and energy supply involved in SIRT3 may be a promising therapeutic strategy for mitochondria-targeted therapy after brain injury." (PMID 37009480, 2023). "However, another study has reported that SIRT3 KO mice exacerbated the carbon tetrachloride (CCl4)-induced acute liver injury model." (PMID 35923224, 2022). "Sirtuin 1 (SIRT1) and SIRT3 play protective roles against cisplatin-induced kidney injury." (PMID 29651144, 2018). "In addition to observations with SIRT6, it was demonstrated in a mouse model that low molecular weight fucoidan inhibited oxidative stress and mitochondrial dysfunction through the upregulation of the expression of SIRT3 after traumatic brain injury." (PMID 28635654, 2017). "The protective effects of SIRT1, SIRT3, and SIRT5 against cisplatin-induced kidney injury have been reported." (PMID 38034992, 2023). "A study showed that SIRT3-defcient mice increased the inflammation response and NLRP3 inflammasome activation in endotoxin-induced acute lung injury." (PMID 35923224, 2022).